CD248 (CD248 molecule)
Diseases named in the same sentence as CD248 in open-access papers (continued):
Sharing a sentence is not in itself a finding about the gene and the disease.
uterine leiomyosarcoma (3 papers, 2019 to 2024). "CD248 expression was highest in liposarcomas and lowest in leiomyosarcomas and was positively correlated with PDGFR-β and heparin sulfate proteoglycan 2 and negatively correlated with carbonic anhydrase IX." (PMID 30847027, 2019).
Aortic dissection (2 papers, 2024 to 2025). Aortic dissection refers to a tear in the intimal layer of the aorta causing a separation between the intima and the medial layers of the aorta. "In Ang II‐induced pressure overload and vascular remodelling, CD248 deficiency attenuates p38 signalling and collagen production, resulting in weakened aortic wall support and an increased risk of aortic dissection." (PMID 40415469, 2025).
autoimmune disease (2 papers, 2023 to 2024). A disorder resulting from loss of function or tissue destruction of an organ or multiple organs, arising from humoral or cellular immune responses of the individual to their own tissue constituents. "Therefore, CD248 may act as a marker of inflammatory MSCs switching from an immunosuppressive to a more aggressive phenotype involved in autoimmune diseases (and cancers)." (PMID 37298499, 2023).
chronic kidney disease (2 papers, 2019 to 2020). Impairment of the renal function secondary to chronic kidney damage persisting for three or more months. "In human chronic kidney disease, upregulated CD248 in myofibroblasts is linked to poor renal survival." (PMID 33033277, 2020). "Thus, CD248 defines a subset of myofibroblasts linked to albuminuria and tubulointerstitial damage during tissue remodeling in chronic kidney disease." (PMID 30847027, 2019).
diabetic nephropathy (2 papers, 2024 to 2025). "Global KO of CD248 attenuated glomerular injury, including albuminuria, supporting the view that communication among glomerular cell types mediates diabetic nephropathy." (PMID 38778209, 2024).
gastric cancer (2 papers, 2015 to 2019). A primary or metastatic malignant neoplasm involving the stomach. "P2RY2, Ephbl and CD248 were explored for gastric cancer detection." (PMID 30847027, 2019). "Genes highly expressed in gastric cancer were CD248, NSDl, RABl7, ABCG8, Ephbl and P2RY2." (PMID 30847027, 2019).
idiopathic pulmonary fibrosis (2 papers, 2016 to 2019). Idiopathic pulmonary fibrosis (IPF) is a nonneoplastic pulmonary disease that is characterized by the formation of scar tissue within the lungs in the absence of any known cause. "The role of CD248 in idiopathic pulmonary fibrosis (IPF) was investigated using IPF lung samples and in cultured pulmonary fibroblasts and epithelial cells." (PMID 30847027, 2019).
IgA nephropathy (2 papers, 2022 to 2025). "Our study revealed significantly increased expression of CD248 in DN renal tissues compared with that in patients with IgA nephropathy, membranous nephropathy, and minimal change disease, which is possibly related to vascular formation in DN patients." (PMID 40451785, 2025). "Moreover, they reported increased CD248 expression in IgA nephropathy, with higher expression levels observed in the later stages of the disease; additionally, clinical follow-up indicated that CD248 is an independent predictor of renal survival." (PMID 40451785, 2025).
Insulin resistance (2 papers, 2022 to 2025). Increased resistance towards insulin, that is, diminished effectiveness of insulin in reducing blood glucose levels. "CD248 has been shown to directly interact with the insulin receptor, blocking binding to insulin and promoting insulin resistance in mice." (PMID 40229590, 2025).
keloid (2 papers, 2024 to 2025). An irregularly shaped, elevated mark on the skin caused by deposits of excessive amounts of collagen during wound healing. "scRNA‐seq also revealed that TEM1 (CD248), a transmembrane protein enriched in scar fibroblasts, enhances TGF‐β signaling via receptor stabilization; its knockdown reduces ECM production in vivo, and therapeutic blockade via ontuxizumab has been shown to be effective in suppressing keloid growth." (PMID 41049267, 2025).
metabolic syndrome (2 papers, 2023 to 2025). A cluster of metabolic risk factors for CARDIOVASCULAR DISEASES and TYPE 2 DIABETES MELLITUS. "These previous findings suggest that HFD stress is required to induce a metabolic syndrome phenotype in the absence of Cd248." (PMID 37115796, 2023).
myocardial infarction (2 papers, 2025 to 2026). Gross necrosis of the myocardium, as a result of interruption of the blood supply to the area, as in coronary thrombosis. "For example, CD248+ fibroblasts were identified by Professor Xinyang Hu’s team as a subpopulation specifically involved in adverse remodeling during the mid-to-late stages after myocardial infarction." (PMID 41403700, 2025).
Peritoneal Fibrosis (2 papers, 2020 to 2025). Disorder characterized by a wide range of structural changes in PERITONEUM, resulting from fibrogenic or inflammatory processes. "CD248 is up-regulated in myofibroblasts of mouse models of renal and peritoneal fibrosis, and CD248 knockdown can alleviate renal and peritoneal fibrosis." (PMID 41382249, 2025). "CD248 was upregulated in myofibroblasts in murine models of renal and peritoneal fibrosis." (PMID 33033277, 2020). "Cd248 knockout (Cd248–/–) could attenuate both renal and peritoneal fibrosis." (PMID 33033277, 2020).
systemic sclerosis (2 papers, 2018 to 2019). A chronic disorder, possibly autoimmune, marked by excessive production of collagen which results in hardening and thickening of body tissues. "When CD248 expression was silenced by means of siRNA in mesenchymal stem cells from systemic sclerosis patients, TGF‐β and PDGF profibrotic signalling was reduced." (PMID 31287944, 2019).
Ureteral obstruction (2 papers, 2015 to 2020). Obstruction of the flow of urine through the ureter. "Although the precise mechanism is not yet known, it is clear that genetic loss of CD248 significantly reduces the formation of matrix depositing myofibroblasts in response to renal injury by ureteric obstruction, resulting in less tissue fibrosis." (PMID 26633297, 2015).
adhesive capsulitis (1 paper, 2019). "Further sub analysis of tissue distribution revealed that PDPN was most abundantly expressed in adhesive capsulitis with approximately 60% of cells positive versus 40% in control tissues followed by CD248 (60% versus 25% control, p<0.01) and VCAM (20% versus 5% control, p<0.01)." (PMID 31013287, 2019).
end-stage renal failure (1 paper, 2015). "In human disease, increased expression of CD248 by stromal cells predicts progression to end-stage renal failure." (PMID 26633297, 2015).
head and neck squamous cell carcinoma (1 paper, 2025). A squamous cell carcinoma that arises from any of the following anatomic sites: lip and oral cavity, nasal cavity, paranasal sinuses, pharynx, larynx, and salivary glands. "In addition, CD248 mRNA and protein levels were assessed in a series of head and neck squamous cell carcinoma (HNSC) cell lines using qRT-PCR and Western blot." (PMID 40276611, 2025).
hepatic cirrhosis (1 paper, 2022). "First, we confirmed that CD248 expression was upregulated in the fibrotic liver tissues of both patients with hepatic cirrhosis and in CCl4-induced mice." (PMID 35317721, 2022).
Hypertension (1 paper, 2021). The presence of chronic increased pressure in the systemic arterial system. "CD248 has become an attractive target for hypertension, but this gene might be novel target for GDM." (PMID 33890634, 2021).
hypertrophy (1 paper, 2023). Hypertrophy is the increase in the volume of an organ or tissue due to the enlargement of its component cells. "On the basis of mouse scRNA-seq data, several subpopulations of fibroblasts, e.g., fibroblast-Thbs4, fibroblast-Wif1, fibroblast-Cd248 and fibroblast-vegfd, were found in hypertrophy heart." (PMID 36805782, 2023).
invasive ductal carcinoma (1 paper, 2020). "For validation, the feature and spatial feature plots of MAF, CD248, GJA1, LAMA3, TJP1, LAMC2, and COL17A1 demonstrated to show the location in BRCA samples, and they were highly-expressed in the invasive ductal carcinoma tissue (cluster 2, 4, 7, 9, 12)." (PMID 33585235, 2020).
liposarcoma (1 paper, 2019). A usually painless malignant tumor that arises from adipose tissue. "Further evidence for CD248 expression by tumor cells came in 2005 with immunostaining of malignant fibrous histiocytoma and liposarcoma showing tumor cell immunoreactivity." (PMID 30847027, 2019).
liver cirrhosis (1 paper, 2022). "CD248 expression was upregulated in patients with liver cirrhosis and in CCl4-induced mice, and was mainly expressed on alpha smooth muscle actin (α-SMA)+ myofibroblasts." (PMID 35317721, 2022).
liver disease (1 paper, 2016). "Expression levels of CD248 mRNA were higher in human cirrhotic end-stage liver disease (3.85-fold difference; p<0.01) as compared with normal human liver." (PMID 26078290, 2016).
myocarditis (1 paper, 2026). Myocarditis is a condition that is characterized by inflammation of the heart muscle (myocardium). "Future studies will specifically evaluate CD248-targeting strategies in chronic myocarditis models to determine whether combinatorial or context-dependent targeting approaches might optimize therapeutic outcomes across the spectrum of fibrotic cardiovascular diseases." (PMID 41356193, 2026).
osteoporosis (1 paper, 2025). A condition of reduced bone mass, with decreased cortical thickness and a decrease in the number and size of the trabeculae of cancellous bone (but normal chemical composition), resulting in increased fracture incidence. "This study revealed a new tendon stem cell subcluster, CD248+ TSPC, with low stemness induced by osteoporosis, which contributes to a weakened rotator cuff that is susceptible to damage and prone to retearing after surgical repair." (PMID 40536433, 2025). "The consistent expression patterns of key genes such as Col14a1 and CD248 in TSPC‐0 and their alignment with the pseudotime trajectory underscore their potential roles in the pathophysiology of osteoporosis." (PMID 40536433, 2025).
pancreatic cancer (1 paper, 2017). "CLEC14A and CD248 can bind MMRN2 simultaneously and this occurs at the interface between endothelium and pericytes in human pancreatic cancer." (PMID 28671670, 2017).
pulmonary arterial hypertension (1 paper, 2021). Pulmonary arterial hypertension (PAH) is a group of diseases characterized by mean pulmonary artery pressure >20 mmHg and elevated pulmonary arterial resistance leading to right heart failure. "REFERENCE 1 Xu T, Shao L, Wang A, Liang R, Lin Y, Wang G, Zhao Y, Hu J, Liu S. CD248 as a novel therapeutic target in pulmonary arterial hypertension." (PMID 34323428, 2021).
rotator cuff tears (1 paper, 2021). "Fibroblasts isolated from rotator cuff tears demonstrate increased expression of the activation markers PDPN, VCAM1 and CD248.." (PMID 35096791, 2021).
Salmonella Infections (1 paper, 2021). Infections with bacteria of the genus SALMONELLA. "In a Salmonella infection model, CD248-deficient mice exhibited reduced thymus size and poor thymus regeneration, indicating a specific but poorly understood role for CD248 expression by mesenchyme in controlling the recovery of thymus function following acute thymus atrophy." (PMID 33717173, 2021).
tumor (104 papers, 2008 to 2025). "In this study, the role of CD248 in pan-cancer was analyzed through diverse tumor-associated databases, such as the Human Protein Atlas Database, the GEPIA2 Database, the cBioPortal Database, the TIMER Database, the STRING tool, and so on." (PMID 40276611, 2025). "CD248 expression was positively related to tumor mutation burden (TMB) in LGG (P = 0.0043), while negatively related to TMB in KIRP (P = 0.0009) and CHOL (P = 0.0028)." (PMID 40276611, 2025). "Endosialin (CD248/TEM-1), a transmembrane glycoprotein overexpressed on tumor-associated pericytes, has been paradoxically linked to both pro-fibrotic progression and vascular destabilization." (PMID 40786514, 2025). "Specific targeting of tumor associated CD248 has naturally given way considering its apparent tumor specificity." (PMID 38468017, 2024). "This gross difference in size was explained by depletion of tumor associated vasculature, increased dysfunctional vessels, and increased intratumoral hypoxia via loss of CD248 positive pericyte coverage and downregulation of WNT signaling pathway." (PMID 38468017, 2024). "According to our results, tumour metastasis was substantially more frequent in WT mice than in CD248‐deficient mice." (PMID 39164826, 2024). "Based on our findings, tumor growth was substantially enhanced in WT mice relative to CD248-deficient mice (p = 0.0476)." (PMID 38906929, 2024). "Our findings revealed that tumour metastasis was substantially greater in WT mice than in CD248‐deficient mice." (PMID 39164826, 2024). "CD248, which is expressed by tumor-associated stromal cells, is coexpressed by two angiogenic factors (OPN and SERPINE1) in lung cancer models." (PMID 37686288, 2023). "Though mapped to lncRNA RP11-867G23.13, CpG site cg10816169 was also close to the gene CD248, which encoded transmembrane glycoprotein functioning as a receptor in tumour angiogenesis." (PMID 35708873, 2022). "For example, CD248 expressed in tumor-associated pericytes facilitates distal dissemination in a contact-dependent manner, thereby increasing circulating tumor cell numbers." (PMID 36401329, 2022). "CD248 has been reported to be expressed by tumor vessel-associated pericytes and stromal fibroblasts in a wide variety of human tumors with different histologies, but not in normal vessels." (PMID 34869004, 2021). "CD248 has also been classified as a marker of tumor vessel-associated pericyte cells and as a selective endothelial precursor cell marker." (PMID 34869004, 2021). "CD248 is a member of this family and is expressed by some tumor-associated fibroblasts and pericytes." (PMID 30847027, 2019). "CD248 is an activation marker of mesenchymal lineage cells including tumor-associated pericytes, stromal myofibroblasts, and activated vascular smooth muscle cells (VSMC)." (PMID 30847027, 2019). "Thrombomodulin, CD93 and CLEC14A can be expressed by endothelial cells, whereas CD248 is expressed by vasculature associated pericytes, activated fibroblasts and tumour cells among other cell types." (PMID 31287944, 2019). "CD248 is expressed on tumor-associated microvascular pericytes, tumor-associated stromal cells and on malignant cells of mesenchymal origin." (PMID 30847027, 2019). "Application of the CD248-specific antibody MORab-004 in a mouse xenograft model caused a decrease in primary tumour growth." (PMID 27916653, 2017). "Higher CD248 expression has been associated in tumour-associated fibroblasts and pericytes while in normal stroma CD248 is hardly detectable." (PMID 27080864, 2016). "One such protein, CD248, is expressed on tumor associated pericytes and tumor stromal fibroblasts and was identified as a potential anti-tumor vasculature target due to its tight association with tumor neovasculature." (PMID 26327620, 2015). "It has been demonstrated in cancer studies that CD248 expression is associated with tumor progression and metastasis." (PMID 26633297, 2015).
tumor (continued). "Tumor Endothelial Marker-1 (TEM1/CD248) is a tumor vascular marker with high therapeutic and diagnostic potentials." (PMID 25051365, 2014). "Most notably, in two tumor cell lines and in cancer associated fibroblasts, the regulation of expression of CD248 was resistant to TGFβ." (PMID 24555435, 2014). "A striking observation made by investigators who previously evaluated CD248-deficient mice in tumor models was the smaller tumor size associated with a seemingly paradoxical increase in microvessel density." (PMID 21549007, 2011). "Therefore, in our work, multi-dimensional evidence proved that CD248 + mr-CAFs are associated with angiogenesis, a hallmark of tumor malignancy in ESCC." (PMID 39334513, 2024). "Moreover, much like CD93, CD248, TM, and CLEC14a, selectins and select galectins have been implicated in tumor angiogenesis and metastasis, the mechanisms of which expand the possibilities of study for the CTLDs at hand." (PMID 38468017, 2024). "Loss-of-function studies in mice implied CD248 promoted tumor growth and inflammation." (PMID 36119065, 2022). "Expression of PSMA and CD248 in tumor-associated vasculature of UCB patients (n = 124)." (PMID 34869004, 2021). "On the basis of the previous results, we performed Spearman correlation analysis on the data, and the results showed that the expression of CD248 in the tumor-associated vasculature correlated significantly and positively with PSMA expression (r = 0.3935, P < 0.0001)." (PMID 34869004, 2021). "Among the 124 cases, PSMA and CD248 were confirmed to be expressed in tumor-associated vessels." (PMID 34869004, 2021). "Importantly, CD248 is overexpressed specifically in tumor-associated fibroblasts and pericytes residing in tumor blood vessels, but is barely expressed in normal tissues, making CD248 an oncofetal protein with potential as a biomarker and therapeutic target." (PMID 34869004, 2021). "Both PSMA and CD248 are specifically expressed in the tumor-associated vasculature of UCB." (PMID 34869004, 2021). "It has been reported that CD248 may be expressed by endothelial progenitor cells and tumor EC, together with pericytes and tumor-associated fibroblasts, during active cancer angiogenesis." (PMID 30285896, 2018). "Endosialin/CD248 is expressed in tumour-associated pericytes (Valdez, Maia, and Conway, 2012)." (PMID 27916653, 2017). "The reduced α-SMA expression on MORAb-004 treated tumor blood vessels could be either a mere association with reduced CD248 expression or a direct consequence of CD248 reduction, meaning CD248 directly regulates α-SMA expression on pericytes." (PMID 26327620, 2015). "Although TGFβ does not appear to directly participate in enhancing CD248 expression during late tumorigenesis, loss of its ability to suppress CD248 may be relevant in tumor progression and metastasis." (PMID 24555435, 2014). "However, CD248 is frequently upregulated in tumors, with particularly high expression in tumor associated stromal fibroblasts in sarcomas and primary and secondary brain tumors." (PMID 21549007, 2011). "Tumor size was similar to that seen with CD248-deficient mice." (PMID 21549007, 2011). "Studies with CD248-deficient mice indicate that CD248 is necessary for tumor growth." (PMID 21549007, 2011). "In addition, CD248 expression was associated with endothelial cell and hematopoietic stem cell infiltration, suggesting that CD248 was likely linked to angiogenesis in the tumor microenvironment (TME)." (PMID 40276611, 2025). "It is well known that CD248 is expressed on the surface of cells of mesenchymal origin, including tumor-associated pericytes and activated fibroblasts, which are thought to play a key role in the development of tumor neovascular networks and stromal interaction." (PMID 30285896, 2018).